GCG (glucagon)
Diseases named in the same sentence as GCG in open-access papers (continued):
Sharing a sentence is not in itself a finding about the gene and the disease.
type 1 diabetes (continued). "Although acute administration of glucagon to hypoglycemic type 1 diabetes patients is an effective treatment to stimulate endogenous glucose production, its role in the endogenous CRR in type 1 diabetes is limited due to pancreatic alpha- and beta-cell failure." (PMID 34444787, 2021). "It has been reported that individuals with type 1 diabetes, as opposed to nondiabetic individuals, secrete glucagon after mixed‐meal stimulations and oral glucose tolerance tests." (PMID 34405569, 2021). "A new version of UVA/PADOVA Type 1 Diabetes Simulator modifies Dalla Man’s model by incorporating glucagon secretion/action/kinetics and nonlinear increase in insulin dependent glucose utlization as BGL dips below the normal range." (PMID 32155149, 2020). "In normal situations, hypoglycemia triggers a counter-regulatory response in the α cells (stimulation of glucagon release with resultant increase in hepatic glucose production), but this does not occur in many type 1 diabetes (T1D) and some T2D patients." (PMID 30415925, 2019). "By reducing the paradoxical increase in glucagon, SIRT1 activation may offer a new, α-cell centric approach to the treatment of type 1 diabetes." (PMID 30228292, 2018). "Unlike insulin-producing ß cells that are destroyed in type 1 diabetes, not only are α cells preserved but become hyperplastic with inappropriately high circulating plasma glucagon that substantially contribute to the hyperglycaemia of this disorder." (PMID 30228292, 2018). "This has been previously observed in subjects with type 1 diabetes where infused insulin did not suppress α-cell production of glucagon, but also in subjects that had tight glycaemic control." (PMID 29494594, 2018). "The consensus conclusion from the total body of work is that complete lack of insulin, as in severe long-standing type 1 diabetes, locks the liver in a state where blunting of glucagon action is unable to downregulate glucose production." (PMID 28323959, 2017). "Glucose-dependent insulinotropic polypeptide (GIP) dose-dependently increases glucagon secretion under euglycemic and hypoglycemic conditions in healthy individuals and in people with type 1 diabetes (T1D) and T2D, with no direct effect on insulin secretion in healthy individuals." (PMID 40964167, 2025). "In addition, several studies have found that GLP-1 receptor agonists did not compromise the hypoglycaemic glucagon response in healthy individuals and individuals with type 1 diabetes." (PMID 40374968, 2025). "The median cytoplasmic area was reduced in glucagon-positive cells (96.07 μm2 vs 75.15 μm2 vs 76.37 μm2 for non-diabetic donors vs donors with short-duration type 1 diabetes vs donors with long-duration type 1 diabetes, respectively) while the nuclear area remained comparable in all donor groups." (PMID 39404844, 2024). "In studies of human pancreata from patients with type 1 diabetes, the frequency of insulin/glucagon bihormonal islet cells was found to be higher than in non-diabetics, suggesting that a similar regenerative pathway might also exist." (PMID 39456933, 2024). "That finding was highlighted in patients with type 1 diabetes since exogenous GLP-1 administration led to lower fasting glycemia, as evaluated by the reduced calculated isoglycemic meal-related insulin requirement, mainly via decreasing glucagon and somatostatin concentration." (PMID 38612640, 2024). "Hence, the absence of insulin-producing β cells in type 1 diabetes is postulated to impair the rapid triggering of glucagon secretion from α cells." (PMID 37558746, 2023). "These figures are not significantly different from previous years, indicating that the use of glucagon has not signifcantly changed during the period 2014–2021; this is likely due to the increase in prevalence of type 1 diabetes and to a small parallel increase of sale of glucagons." (PMID 36550552, 2022).
type 1 diabetes (continued). "Of note, α cells from donors with type 1 diabetes (T1D) showed decreased ARX expression compared with α cells from nondiabetic donors, indicating that this factor may contribute to impaired glucagon secretion observed in T1D." (PMID 34428183, 2021). "As previously reported, lipopolysaccharide infusion combined with insulin reduction resulted in profound glucagon responses in individuals with type 1 diabetes, resembling those seen in nondiabetic individuals, and demonstrating intact glucagon responsiveness to systemic inflammation." (PMID 34405569, 2021). "However, in people with type 1 diabetes, this increase in plasma glucagon in the absence of sufficient insulin has been shown to cause postprandial hyperglycaemia." (PMID 26202844, 2015). "Therefore, in patients with type 1 diabetes, secretion of glucagon is significantly increased as there is no inhibition by insulin thus elevating the blood glucose level." (PMID 25853137, 2015). "The relationship between insulin and leptin has been heavily studied, with findings most recently suggesting that leptin has an inhibitory effect on insulin secretion and reduces glucagon secretion in rodents with type 1 diabetes, resulting in improved glycemic control in the absence of insulin." (PMID 24987413, 2014). "Regarding Type 1 diabetes(T1D), animal/islet-cell studies found that GABA promotes insulin secretion, inhibits α-cell glucagon and dampens immune inflammation, while GAD immunization may also preserve β-cells." (PMID 36566274, 2022). "Blood glucose, plasma insulin, and glucagon levels were measured following a duodenal glucose tolerance test (IDGTT), in four pigs with STZ-induced type 2 diabetes (T2D pigs) and in four pigs with STZ-induced type 1 diabetes (T1D pigs)." (PMID 33294459, 2020). "In the DK/DKA group, a negative correlation was seen between the plasma glucagon level and the serum C-peptide immunoreactivity (CPR)/plasma glucose ratio in type 1 diabetes patients (n = 26) (ρ = − 0.67, P = 0.0002)." (PMID 41292690, 2026). "Short-term dapagliflozin treatment in type 1 diabetes increases plasma ketone concentrations without affecting the secretion of GLP-1, glucagon or somatostatin." (PMID 40629004, 2025). "Glucagon-positive, PC1/3-negative cells were also increased in islets from donors with type 1 diabetes (2.04% vs 9.29% vs 11.73% for non-diabetic donors vs donors with short-duration type 1 diabetes vs long-duration type 1 diabetes, respectively)." (PMID 39404844, 2024). "However, to date, most interventions that have improved the autonomic response to hypoglycaemia in people with type 1 diabetes and IAH, such as hypoglycaemia avoidance, have not shown a similarly enhanced glucagon response." (PMID 38010533, 2024).
Hyperinsulinemia (96 papers, 2006 to 2026). An increased concentration of insulin in the blood. "The inhibitory effect of hyperinsulinism on glucagon is two-fold: mutation of the KATP channel affects alpha cell membrane potential/ glucagon secretion and high circulating insulin levels directly inhibiting secretion by the alpha-cell." (PMID 32735622, 2020). "Long-acting glucagon preparations, such as zinc protamine glucagon, have been used to treat glucagon deficiency states or in combination with somatostatin to address congenital hyperinsulinemia." (PMID 40119223, 2025). "Finally, we believe that the large size and the resulting prolonged exposure to elevated glucose levels can cause the shutdown of glucagon-producing α cells, resulting in hyperinsulinemia, poor glycemic control, and increased frequency of hypoglycemic episodes." (PMID 35651551, 2022). "On the other hand, some proteins are stimulates of glucagon secretion which can increase hepatic glucose production thus resulting in both hyperinsulinemia and hyperglucagonemia." (PMID 41602572, 2026). "The absence of acidosis, reduced levels of beta‐hydroxybutyrate and non‐esterified fatty acids, and the response to glucagon infusion led to the diagnosis of hyperinsulinism." (PMID 41030468, 2025). "In infants with low glucose and low BOHB concentrations, CHI (as well as other forms of hyperinsulinism) should be considered and a work-up focusing on family history, physical exam, obtaining a critical sample, and a glucagon challenge test is indicated." (PMID 38792494, 2024). "Glucagon deserves more detailed exploration as an alternative acute treatment, since hepatic glycogen stores will be retained in hyperinsulinism and glucagon can promptly raise plasma glucose levels for 1–2 h or more." (PMID 36969273, 2023). "A glucagon test should be performed following the critical sample to further evaluate hyperinsulinism, which is supported by an increase in BG of 30 mg/dL (1.67 mmol/L) or higher." (PMID 37404330, 2023). "In summary, our data demonstrate that IV-infused C-peptide preserves basal glucagon secretion during euglycemic-hyperinsulinemia in dogs, thereby suggesting that it plays a role in intraislet signaling and the in vivo regulation of glucagon secretion." (PMID 34003799, 2021). "The analysis of metabolite pathway enrichment showed a disturbed glucagon signal pathway, consistent with the phenomenon of hyperinsulinemia in hypertensive patients." (PMID 34026879, 2021). "Hyperinsulinemia was ameliorated with insulin and glucagon levels being lower after probiotic ingestion and concentration of antidiabetic hormones GLP-1 and PYY was augmented after probiotic supplementation." (PMID 33802371, 2021). "In response to euglycemic-hyperinsulinemia, glucagon secretion decreased in SAL but remained unchanged from the basal period in CPEP condition." (PMID 34003799, 2021). "According to this, a study in patients reported hyperinsulinism but elevated postprandial glucagon secretion after RYGB." (PMID 34575329, 2021). "The mechanism of defective autophagy is likely to be dependent on hormonal factors, since not only sustained hyperinsulinemia and mTORC1-mediated signaling were observed in U neonates, but also the levels of glucagon were decreased at birth." (PMID 33077861, 2020). "Congenital hyperinsulinism was diagnosed through a combination of clinical and laboratory findings, including clinical presentation, hyperinsulinism, low serum ketone bodies, low serum fatty acids with increase of blood sugar levels after glucagon injection." (PMID 32537058, 2020). "GIR reduced in 50% of those requiring surgical treatment indicating that the effect was directly attributable to glucagon and therefore unlikely due to a reduction in severity of hyperinsulinism." (PMID 33013678, 2020). "In a mice study, chronic exposure to Aroclor 1254 (a mixture of PCB congeners) induced hyperinsulinemia with an elevation of glucose and glucagon levels." (PMID 28898241, 2017).
Hyperinsulinemia (continued). "Yet, given that glucagon modulates insulin release, the potential contribution of altered glucagon levels to the β-cell hypersecretion and hyperinsulinemia of GC-treated subjects remains to be investigated." (PMID 24705399, 2014). "Hyperinsulinemia and hyperglucagonemia are frequently present in cirrhotic patients where glucagon is disproportionately increased resulting in an elevated glucagon/insulin ratio." (PMID 21234351, 2010). "The results demonstrated that maternal insulin resistance and hyperinsulinemia impair endocrine pancreas development and lead to metabolic disturbances in offspring, including higher postnatal glucose, insulin, leptin, glucagon, and GLP-1 levels, along with reduced β-cell area and proliferation." (PMID 41007299, 2025). "By contrast, a study on healthy people showed that eating a mixed meal containing propionic acid led to an increase in plasma glucagon, fatty-acid-binding protein 4, and norepinephrine concentrations, leading to glucagon-induced insulin resistance, resulting in compensatory hyperinsulinemia." (PMID 38930856, 2024). "Furthermore, a subgroup of individuals with MASLD presented a lipid-induced impairment of hepatic sensitivity, not only to insulin but also to glucagon, resulting in both hyperglucagonemia and hyperinsulinemia." (PMID 39459592, 2024). "Our patient's glucose response to glucagon was lower than expected for hyperinsulinism, which may be explained by the simultaneous presence of growth hormone deficiency." (PMID 37404330, 2023). "This lipodystrophic phenotype was associated with impaired whole-body metabolic function, as judged by slightly reduced glucose tolerance and hyperinsulinemia, as well as a trend towards increased glucagon levels (2.61 ± 0.33 vs. 4.44 ± 0.97 pmol/L, p = 0.122)." (PMID 35760318, 2022). "We tested the hypothesis that C-peptide infusion would enhance glucagon secretion in response to hyperinsulinemia during euglycemic and hypoglycemic conditions in dogs (5 male/4 female)." (PMID 34003799, 2021). "Thus, altered neonatal regulation of hepatic glucose output from glycogen stores is likely to be primarily related to hyperinsulinemia along with blunted counterregulatory glucagon response." (PMID 33077861, 2020). "Our work-up to differential diagnosis showed hyperinsulinism (high insulin plasma level, hypoketonaemia, hypofattyacidaemia at lower glucose level, high glucose requirement to maintain normoglycaemia, and positive glycaemic response to glucagon)." (PMID 26064751, 2015). "Interestingly, we found that in DEX rats, the glucagon levels were higher under conditions of augmented blood glucose levels and hyperinsulinemia." (PMID 24705399, 2014). "In addition, in one of the original studies of glucagon as an aid in the diagnosis of hyperinsulinism, the authors concluded that occasionally a blunted glucose response may be seen." (PMID 37404330, 2023). "These modifications could be related to EA regulation of endogenous glucose production and glucose metabolism; however, other measurements such as glucagon, which is regulated by glucose and suppressed by hyperinsulinemia, could be useful to a wide pathophysiological comprehension." (PMID 36233611, 2022). "However, after metabolically challenged with a high-fat diet, Smn(+/−)mice display abnormal localization of glucagon-producing alpha-cells within the pancreatic islets, increased number of insulin-producing beta cells, hyperinsulinemia and increased hepatic glucagon sensitivity." (PMID 29473878, 2018). "While hyperinsulinemia is a common finding in HFD-fed animals, data on circulating glucagon concentrations are contradictory, showing increase, decreases or no changes." (PMID 36768493, 2023).
Hyperinsulinemia (continued). "Interestingly, these investigators hypothesized that this metabolic phenotype might be an early adaptive response to the eventual progression to T2DM, allowing normoglycemia not only due to the compensatory hyperinsulinemia produced by β-cells, but also by lowering glucagon secretion by α-cells." (PMID 34572095, 2021). "To determine whether the effects of glucagon or epinephrine on VPK were related to the expected hyperinsulinemia following hormone treatment, we performed hyperinsulinemic-euglycemic clamps to match plasma insulin concentrations to those measured in the epinephrine- and glucagon-treated rats." (PMID 27002151, 2016). "The increase in glucagon secretion and subsequent stimulation of HGO can also stimulate insulin secretion, which could explain the hyperinsulinemia found in patients despite the inhibitory effect of SGAs on GSIS in the initial stages of the treatment." (PMID 31671770, 2019). "In contrast to glucagon- or epinephrine-treated rats, hyperinsulinemia suppressed hepatic glucose production but did not change VPyr-Cyc/VMito." (PMID 27002151, 2016). "Similar to other previously addressed responses, glucagon never returned to baseline values and remained depressed, which may be explained by the concurrent hyperinsulinemia that remained above baseline until the cessation of the trial." (PMID 31689951, 2019). "In addition to basal hyperinsulinemia, mice fed HFD for 15 weeks showed significantly increased leptin and PAI-1 levels, together with lower circulating concentrations of adiponectin, ghrelin and glucagon." (PMID 30382123, 2018). "Thus, glucagon seems to exert a positive modulatory effect on insulin secretion under basal glucose concentrations in DEX rats, and this action may be involved in the fasting hyperinsulinemia observed after GC treatment." (PMID 24705399, 2014).